HIF1A (hypoxia inducible factor 1 subunit alpha)
Diseases named in the same sentence as HIF1A in open-access papers (continued):
Sharing a sentence is not in itself a finding about the gene and the disease.
breast cancer (continued). "Furthermore, murine mammary tumour cells from mice with Cre-loxP-mediated inactivation of HIF-1α failed to reach the logarithmic growth phase under low oxygen conditions." (PMID 19223895, 2009). "In breast cancer, diffuse type of HIF-1α overexpression is probably non-functional." (PMID 16035955, 2005). "Consequently, the persistent hypoxic microenvironment and HIF-1α stabilization significantly contribute to the aggressive nature and therapeutic resistance of TNBC, underscoring the need for targeted strategies to mitigate hypoxia-driven pathways in this challenging breast cancer subtype." (PMID 41526224, 2026). "Additionally, in breast cancer, there’s evidence of alteration in metabolism to a glycolytic type through the transforming growth factor-β (TGF-β)-STAT1-succinate dehydrogenase (SDH)-hypoxia-inducible factor 1α (HIF1α) pathway, both in ex vivo and in vivo murine models." (PMID 38541208, 2024). "Indeed, ATRA induces the expression of HIF-1α (Hypoxia-Inducible Factor 1-alpha) and VEGF in certain solid tumors and the ATRA/HIF-1α/VEGF pathway has been reported to promote tumor angiogenesis in HUVEC co-cultures and xenografts of the MCF-7 breast cancer cell line." (PMID 38360674, 2024). "Moreover, comparative studies of HIF-1α and CAIX protein expression in the same large mature breast cancer cohort, using optimal methodological approaches, are required to be carried out to confirm this or if whether a combination of these markers should be employed." (PMID 37061698, 2023). "In addition, HIF1α also plays key roles in promoting CSC phenotypes through ITGA6 forkhead box protein M1 (FOXM1), miR-215, and signal transducer and activator of transcription 3 (STAT3) activation in breast cancer, pancreatic cancer, colon cancer, and glioma, respectively." (PMID 34482364, 2021). "We have previously demonstrated that under hypoxic conditions HIF-1α expression was downregulated by miR-204 mimics in breast cancer cells which could explain, in part, the negative effects of miR-204 we found in hypoxia-induced vasculogenic mimicry associated with HOTAIR upregulation." (PMID 32466537, 2020). "However, it is not known whether LNT-mediated tumor suppression in breast cancer involves the interaction between Nur77 and HIF-1α." (PMID 33245358, 2020). "Furthermore, we show that hypoxia induce down-regulation of ERα expression in breast cancer cells (in antiestrogen-resistant cells even approaching the threshold of detection), corroborating our previous data from DCIS lesions where ERα-expression was lost in HIF-1α-positive perinecrotic cells." (PMID 31821370, 2019). "Since the HIF-1α K532-acetylation by NAA10 is known to enhance the pVHL binding to HIF-1α, we examined whether FIH promotes this interaction through NAA10 W38-hydroxylation in HEK293 and a human breast cancer cell line MDA-MB-231, which was used as a representative cancer cell." (PMID 30237125, 2018).
breast cancer (continued). "Likewise, breast cancer cells engineered to overexpress a mutant c-fos, unable to bind the AP-1 sites, failed to induce the up-regulation of HIF-1α in response to estrogen, thus supporting the involvement of the transcription factor c-fos in the transcriptional activation of HIF-1α gene." (PMID 29996493, 2018). "The fact that HIF1α downregulation was observed in the primary breast cancer cells after 24 h, but not after 14 h may indicate that it takes a certain time period to achieve this downregulation and execute the HIF1α-to-HIF2α switch." (PMID 29993038, 2018). "However, we could not observe any effect of ∆Np73 on HIF-1α mRNA levels either in cell lines or in breast cancer patient material." (PMID 29628507, 2018). "Furthermore, we also investigated the stimulatory effects of CoCl2 exposure on the BCSC sphere formation, the size of the CD44+/CD24– subpopulation, and the expression of HIF1α and HIF2α with or without HIF2α inhibitor 76 treatment in other liable human breast cancer cell lines such as MDA-MB-231." (PMID 27270657, 2016). "However, this is not supported by our observation in human breast cancer cells in vitro and in vivo studies on nude mice, which showed that the expression of HIF-1α in the residual tumors is enhanced not only in poor-responders to primary endocrine therapy, but also in good-responders." (PMID 25929338, 2015). "Moreover, the inhibition of LOX, which is induced by HIF-1α in hypoxic breast cancer cells at primary tumours by shRNA, was also effective at preventing the CD11b+ BMDC recruitment, pre-metastatic niche formation and metastatic growth of MDA-MB-231 breast cancer cells at lungs in a mouse model." (PMID 23301832, 2013). "In addition to A431 vulvar squamous carcinoma cells, we found that 1, 9 PA could downregulate HIF-1α in PC3 prostate cancer cells, MDA468 breast cancer cells, MCF7 breast cancer cells transfected with a high level of HER2, and H3255 and HCC827 non-small cell lung cancer cells." (PMID 21209911, 2010). "Clinically, however, evidence remains limited, as studies in humans typically investigate other biomarkers instead of HIF-1α, with no clinical trials directly demonstrating reduced HIF-1α within breast cancer tumors." (PMID 41614951, 2026). "The impact of the WWOX/HIF1A ratio on EMT, invasiveness, and angiogenesis is not confined to breast cancer but extends to brain tumours and HCC as well." (PMID 41007296, 2025). "Hypoxia-induced long non-coding RNA (lncRNA) RAB11B-AS1 is upregulated in numerous human breast cancer cell lines and its expression is induced by canonical HIF-2α signaling but not HIF1α under hypoxic conditions." (PMID 37124241, 2023). "The trial investigated the expression of HIF-1α and HIF-1α regulated genes CA-9, VEGF, and GLUT by immunohistochemistry and mRNA-sequencing in the tumor tissue of breast cancer patients who received daily digoxin for 14 days or no therapy preoperatively." (PMID 36846589, 2023). "To further understand the specific mechanism of HIF-1α ubiquitination induced by HNK, we performed a mass spectrometric detection of breast cancer with and without HNK intervention." (PMID 35350760, 2022). "Metabolic reprogramming can be seen in the requirement of a glycolytic phenotype, mediated by increased HIF-1α activity and PDK1 expression, to enable 4T1 breast cancer cells to metastasize to the liver, rather than to the bones or lungs." (PMID 35372069, 2022). "In hepatocarcinoma cells, but not in breast cancer cells, GRIA2 and GRIA3 (GluA 2 and 3) mRNA expression is upregulated by hypoxia through HIF-1α and HIF-2α, which contribute to cell proliferation and growth of tumor xenografts." (PMID 36457557, 2022). "The results suggest that plumbagin is unlikely to block HIF-1α signaling and its target genes by interrupting the PI3K/Akt/mTOR signaling pathway in MCF-7 breast cancer cells." (PMID 36080483, 2022).
breast cancer (continued). "As a non-toxic inhibitor of HIF-1a and TGF-b activities, efficient elimination of breast cancer stem cell." (PMID 36591450, 2022). "The Pearson’s correlation analysis of the TCGA dataset containing 1169 breast cancer patients and our in-house dataset containing 110 breast cancer tissues confirmed that HIF-2α, but not HIF-1α, was positively correlated with P-gp and BCRP." (PMID 35301432, 2022). "It was reported that in breast cancer cell lines, ID1 induces HIF-1α/VEGFA protein expression but not HIF-1α mRNA expression; in addition, ID1 enhances the stability of the HIF-1α protein." (PMID 35163396, 2022). "Although there was no expressional correlation between DLEU1 and HIF-1α in breast cancer tissues, overexpressing HIF-1α in shDLEU1 breast cancer cells was sufficient to recover the malignant phenotypes resulting from knocking down DLEU1." (PMID 35853854, 2022). "In cells derived from hepatocarcinoma and renal carcinoma, but not from breast cancer, EAAT1 and EAAT3 expression is upregulated under hypoxic conditions through transactivation of gene expression by HIF-1α and HIF-2α." (PMID 36457557, 2022). "A survey of the breast cancer cell lines MCF-7 and MDA-MB-231 revealed that hyperinsulinemia, not hyperglycemia, drives the activity of the HIF-1α rather than the one-way regulatory mechanism between HIF and glucose." (PMID 36139678, 2022). "Fibroblast-specific HIF-1α, but not HIF-2α, knockout in mouse mammary tumor model resulted in the formation of normal vessel structure and enhanced tumor growth." (PMID 35884382, 2022). "Similar to these observations, our study shows that knockdown of HIF-1α, but not HIF-2α, in breast cancer cells induced a significant decrease in UCA1 expression, suggesting that HIF-1α is a direct regulator of UCA1 in MCF-7 under hypoxic conditions." (PMID 34054950, 2021). "Thus, it could be understood that CBD can inhibit the aggressiveness of breast cancer and be sensitized to more aggressive breast cancer cells by regulating a variety of signaling pathways and immunologic factors related to malignancy as well as Src/VHL/HIF-1α signaling." (PMID 34830821, 2021). "CoCl2-induced hypoxia in breast cancer further promotes HIF-1α mRNA and protein expression while reducing VHL expression (a negative HIF-1α regulator), especially in miRNA-high cell lines." (PMID 32707933, 2020). "Although HIF-1α depletion had no measurable effect on lincNORS levels, HIF-2α knockdown blunted the hypoxic accumulation of lincNORS in breast cancer cells." (PMID 32958772, 2020). "Indeed, HIF-1α could enhance cell proliferation and broke the balance between proliferation and apoptosis, and the increased expression of Ki67 and high level of HIF-1α in cancer predicts poor prognosis in many cancers, such as pancreatic cancer, colorectal cancer, breast cancer, and so on." (PMID 31320912, 2019). "First, β2M activates SGK1 signaling and upregulates Bcl-2 expression, and do not affect HER2, HIF-1α, VEGF, and ERK signaling in ER+ breast cancer cells with HER2−." (PMID 30866857, 2019). "Second, β2M inhibits CREB signaling and the expression of VEGF protein and activates ERK signaling, but does not affect HIF-1α and SGK1 signaling in ER− breast cancer cells with HER2−." (PMID 30866857, 2019). "For the breast cancer cell lines, to our surprise, unlike SKBR3 and MDA-MB-231 cell lines, the triple-negative BT549 cells don’t express HIF-1α." (PMID 30940798, 2019). "Taken together, we report that non-CpG and CpG hypermethylation occurring within the HIF-1α gene promoter around the TSS in MCF-7 cells and luminal subtype breast cancer samples is an important mediator of reduced HIF-1α expression." (PMID 30940798, 2019). "In this study, we found that chronic hypoxia enhanced the resistance of breast cancer cells to PTX and induced high expression of HIF-2α, but not HIF-1α." (PMID 30340507, 2018).
breast cancer (continued). "Global PHD2 haplodeficiency leading to increased stromal HIF-1α and HIF-2α stabilization did not have an effect on primary tumor growth in LLC and pancreatic carcinoma tumor models as well as in the MMTV-PyMT breast cancer metastasis model." (PMID 29896451, 2018). "Most studies characterizing the consequences of HIF-1α and HIF-2α silencing on metabolism have been performed with cancer cells but, to the best of our knowledge, none with breast cancer cells." (PMID 29632647, 2018). "To this end, we transfected MDA-MB-231 and BT-549 breast cancer cells with pre-miR-24 and a FIH1 cDNA lacking the 3′UTR, and analyzed the effect on mammosphere formation, migration and HIF1α expression." (PMID 28061479, 2017). "A positive correlation between tumor HIF-1α protein expression and tumor FDG uptake has also been shown in squamous cell carcinoma of the head and neck and in breast cancer, but to our knowledge not previously in EC." (PMID 27634881, 2016). "Importantly, significant correlations of MCU expression with both HIF1A and its target genes were found, indicating that MCU‐dependent HIF1A transcription may also occur in human breast tumors and that MCU may represent a novel regulator of breast cancer progression." (PMID 27138568, 2016). "The potential of anti-HIF-1α targeted therapy is therefore not a candidate for exclusive use in TNBC, but should be considered in all breast cancers, especially in the setting of clinically aggressive or refractory disease." (PMID 26046764, 2015). "Irrespective of breast cancer subgroup, we similarly did not establish any correlation between HIF-1α expression and age, grade, lymph node status, or MVD, which, when elevated in breast cancer, is thought to indicate an aggressive phenotype." (PMID 26046764, 2015). "Knockdown of HIF-1α did not alter the anoxia induction of TRIB3 expression at any time point, which is in line with our results in breast cancer cells after CoCl2 incubation." (PMID 21864376, 2011). "Consistent with our findings in the basal-breast cancer cell line, AU565 cells (subgroup 7) demonstrated that silencing of HIF1A (HIF-1α), but not EPAS1 (HIF-2α), led to the abolishment of the exaggerated hypoxia response seen in these cells." (PMID 21672245, 2011). "Additional associations with MFI found for thioredoxin and downstream factors of the thioredoxin pathway, including PRDX2, RRM2, HIF1A and VEGF, confirm the importance of the thioredoxin system in breast cancer regardless of its ROS-related or unrelated roles." (PMID 20584310, 2010). "The fact that Mb in breast malignancies links with HIF-2α rather than HIF-1α results perhaps from the mutually exclusive status between active HIF-1α and ERα/PR signalling in breast cancer cells." (PMID 20531416, 2010). "Correlation between HIF-1α, GLUT-1 and other studied biomarkers in primary breast cancer in patients without and after preoperative chemotherapy." (PMID 20569445, 2010). "However, 50 mmHg HP stimulation significantly increased aldehyde dehydrogenase (ALDH) activity and upregulated HIF-1α and stemness markers (CD44 and SSEA-1) in MCF-7 and BT-474 but not in MDA-MB-453 breast cancer cell lines." (PMID 42224096, 2026). "Furthermore, HIF-1α (HIF-2α was not analyzed) shows a lactate-driven oscillatory expression pattern in hypoxic cancer cells, which predicts low survival of breast cancer patients." (PMID 40918648, 2025). "The data suggest that PB, which inhibits the PI3K/Akt/mTOR signaling pathway in MCF‐7 breast cancer cells, is unlikely to interfere with HIF‐1α signaling or its target genes; however, PB may reduce HIF‐1α through an alternative mechanism." (PMID 40842665, 2025). "There may be additional potential mechanisms, independent of HIF-1α, that regulate the expression of UBE2M in ER- breast cancer cells." (PMID 39138151, 2024). "Furthermore, we showed that HIF-2α, but not HIF-1α, was highly expressed in CD44+CD24− breast cancer tissues." (PMID 35301432, 2022).
breast cancer (continued). "HIF1A is known to be regulated downstream from RAP1, although not explicitly in breast cancer." (PMID 35197309, 2022). "HIF-1α can regulate the expression of these noncoding RNAs, and noncoding RNAs can interact with mRNA-HIF-1α to regulate the expression of HIF-1α protein and then induce the progression of many types of tumours, including breast cancer and ovarian cancer." (PMID 35004308, 2021). "Briefly, HIF-1α overexpression, but not FOXP3 nor E2F1, has been reported to be closely related to high histological grade, lymph node metastasis, large tumor size, and increased angiogenesis in breast cancer, which is consistent with the function of JFK." (PMID 34336836, 2021). "Indeed, HIF-1α accumulation was recovered in anoxic (0.1% O2) NRF2-silenced cancer cells and miR-181c overexpressing breast cancer cells (data not shown)." (PMID 31078780, 2019). "FBP1 was also found to be negative correlated with HIF1α activity in HCC and breast cancer." (PMID 29556139, 2018). "This is, however, not mediated by accumulated HIF1α and DEPTOR, as seen in breast cancer cells." (PMID 27063292, 2016). "Consistent with our results, other investigators have reported that, compared to HIF-1α, HIF-2α is more stable under high oxygen tension in non-malignant/malignant cells, and this protein escapes degradation under near-normoxic conditions in breast cancer." (PMID 24194900, 2013). "Interestingly, we failed to observe any changes in HIF-1α mRNA transcript levels for Rac1 transfectants, indicating that Rac-induced HIF-1α expression in breast cancer cells is independent of mRNA regulation." (PMID 21980400, 2011). "Our results clearly indicate that the pharmacological inhibitors of ERα, c-Src, PI3K and mTOR not only inhibited Akt/mTOR pathway, but also inhibited the expression of HIF-1α, confirming the importance of ERα/c-Src/PI3K assembly in the non-genomic signal transduction of E2 in breast cancer lines." (PMID 21897387, 2011). "Although this current study did not directly investigate ERα’s role, the overexpression of HIF-1α observed in both ERα + (Hc7 and Ac1-ExR) and ERα- (LTLTCa) HER2+ breast cancer cell lines, suggests that ERα status may not affect HER2 regulation of non-hypoxic HIF-1α levels." (PMID 24472707, 2014). "However, we found no close relationship between HIF-1α and SDH expression in these breast cancers." (PMID 23888270, 2013).